KRAS (KRas proto-oncogene, GTPase)
Diseases named in the same sentence as KRAS in open-access papers (continued):
Sharing a sentence is not in itself a finding about the gene and the disease.
lung adenocarcinoma (continued). "As a result, KRAS mutations generally affect consistent percentages of Caucasian (21–33%, 21.3% in our series) and to a lesser extend Asian (2–15%) patients with lung adenocarcinoma, representing therefore an attractive target for future treatments." (PMID 35012520, 2022). "In the analysis of different KRAS mutation subtypes in lung adenocarcinoma, it was found that the most common mutant subtype of KRAS was G12C, which was associated with higher TMB and PD-L1 positivity rate compared with wild type KRAS." (PMID 35359599, 2022). "A study of 106 Lebanese patients with lung adenocarcinoma underwent mutational analysis for KRAS in exon 2 codon 12 and 13 alongside exon 3 codon 61 by reverse hybridization." (PMID 36004014, 2022). "Consistent with the mouse data, KRAS mutations in human lung adenocarcinomas displayed different levels of concordance with the mutation spectrum predicted from the mutation signatures." (PMID 35482806, 2022). "CT-based radiomics has predicted the mutation status in patients with CRC and in lung adenocarcinoma patients for KRAS/BRAF and EGFR, respectively." (PMID 36612061, 2022). "Suppression of xCT was demonstrated to cause synthetic lethality in mutant-KRAS lung adenocarcinoma." (PMID 35280777, 2022). "The comutation of STK11/LKB1 and the comutation of KEAP1/NFE2L2 were identified as genomic drivers for primary resistance to immune checkpoint inhibitors in KRAS-mutated lung adenocarcinoma." (PMID 36230855, 2022). "Remarkably, Notch3 overexpression was also observed in KRAS-mutated lung adenocarcinoma cells and correlated positively with aldehyde dehydrogenase (ALDH) expression, resulting in enhanced CSC phenotype." (PMID 35463301, 2022). "Loss of LKB1 activity is prevalent in KRAS mutant lung adenocarcinoma and promotes treatment-resistant tumors and poor survival." (PMID 35210547, 2022). "We report the first documented case series of two lung adenocarcinoma patients demonstrating Kirsten rat sarcoma viral oncogene homolog (KRAS) G12C mutations by reverse transcription-polymerase chain reaction techniques from Saudi Arabia." (PMID 36004014, 2022). "recently reported among a cohort of 1012 patients with a stage I-III lung adenocarcinoma that KRAS G12C mutations are associated with a significant shorter OS and relapse-free survival, compared with other KRAS mutations and wild-type KRAS." (PMID 35251972, 2022). "The aim of the present study was to examine ERα, ERβ and GPER1 expressions, and to evaluate their correlation with clinicopathologic factors and with the frequency of EGFR and KRAS gene mutations in lung adenocarcinoma." (PMID 35664735, 2022). "KRAS-mutant lung adenocarcinomas associated with KEAP1 mutational inactivation demonstrated lower expression rates of PD-L1 and other immune markers, proving refractory to anti–PD-1 antibody therapy." (PMID 36012655, 2022). "In conclusion, our study shows that LOH in KRAS is associated with a favorable prognosis in patients with early-stage lung adenocarcinomas, particularly in patients with KRAS mutated tumors." (PMID 35574381, 2022). "We utilized the KRAS-mutated human lung adenocarcinoma cell lines A549 and H358 and deleted ITGB1 (integrin β1) using CRISPR/Cas9." (PMID 35763345, 2022). "Activating mutations in KRAS occur in ~30% of lung adenocarcinoma (LUAD), the major molecularly-defined subtype of lung cancer." (PMID 36418460, 2022). "Lung adenocarcinoma patients that present with KRAS mutations have a higher mutational burden and co-occurring mutations with tumor suppressors genes." (PMID 35573694, 2022).
lung adenocarcinoma (continued). "KRAS glycine 12 mutated to cysteine (KRAS[G12C]) is an activating KRAS mutant found in ∼12% of lung adenocarcinomas, ∼3% of colon cancers, and a lower frequency in pancreatic adenocarcinomas and other cancers." (PMID 34958800, 2022). "Here, the authors derive a RAS gene expression signature and a machine learning classifier to predict drug response and clinical outcomes in lung adenocarcinoma and other solid tumours, with improved performance over KRAS mutations alone." (PMID 36163168, 2022). "Around 52% of lung adenocarcinoma patients have also been reported as having KRAS G12C mutations, making it quite common." (PMID 36004014, 2022). "The comutations with KRAS were reported to be the primary drivers of molecular and immunological differences in KRAS-mutant lung adenocarcinomas, while specific KRAS mutations (KRASG12C, KRASG12V, KRASG12D, and others) did not have a consistent pattern." (PMID 36230855, 2022). "The frequency of KRAS mutations in lung adenocarcinoma and squamous cell lung carcinoma was 12.8% and 8.0%, respectively." (PMID 35394121, 2022). "The study demonstrates that for patients with early-stage lung adenocarcinomas, loss of heterozygosity in the KRAS region is associated with improved OS as well as RFS." (PMID 35574381, 2022). "New data suggests that KRAS-mutated lung adenocarcinoma can exhibit enhanced PD-L1 expression and additional somatic mutations, linking the prospect of immune checkpoint blockade therapy being applied to the disease." (PMID 36189266, 2022). "KRAS mutation is one of the most frequently mutated genes in several cancers, including lung adenocarcinomas." (PMID 36248982, 2022). "Genomic data analyses evidenced that EGFR and KRAS mutations, the most common aberrations in lung adenocarcinoma, are extremely rare in pure SCC, while alterations in the FGFR kinase family, PIK3CA, CDKN2A and RB1 pathways are common." (PMID 35743191, 2022). "In NSCLC, KRAS mutations are present in approximately 30% of lung adenocarcinomas and 5% of squamous cell carcinomas; these alterations are more common in western (26%) than in Asian (11%) populations and in smokers (30%) than non-smokers (10%)." (PMID 36012655, 2022). "Mutations in KRAS are seen in ~ 27% of lung adenocarcinomas, and in total, ~ 76% of tumors harbor mutations in RTK-Ras-Raf pathway genes including the tyrosine kinases EGFR and MET." (PMID 36522653, 2022). "In mutant KRAS lung adenocarcinoma mouse models, constitutive deficiency of LKB1, a known upstream regulator of AMPK, was associated with impairment of FAO, due to inactivation of the AMPK–ACC axis and ROS accumulation." (PMID 35159223, 2022). "KRAS is present in a mutated form in 80% of pancreatic cancers, 40% of colorectal cancers, and about 30% of lung adenocarcinomas." (PMID 36012655, 2022). "KRAS mutations occur in 31% of unresected treatment-naïve lung adenocarcinomas and involve multiple cellular pathways." (PMID 36430528, 2022). "In conclusion, our data suggest that, just as nontransformed epithelial cells require integrin-mediated adhesion signaling for survival, KRAS-mutated lung adenocarcinomas maintain this requirement for cell survival and proliferation." (PMID 35763345, 2022). "We report two cases of lung adenocarcinoma harboring KRAS G12C mutations, which are the first to be reported in the Arabian Gulf according to our literature review." (PMID 36004014, 2022). "HG106, recently known as a potent SLC7A11 inhibitor, also showed marked tumor suppression and prolonged survival in the preclinical mouse models of KRAS-mutated lung adenocarcinoma." (PMID 36552652, 2022).
lung adenocarcinoma (continued). "The KRAS mutation being mainly present in lung adenocarcinoma (13/16 for the lung, 2/16 for the rectosigmoid and 1/16 for the jejunum), we performed a multivariate analysis on just the lung patient population." (PMID 36163026, 2022). "A single amino acid substitution in the KRAS protein due to a single nucleotide substitution mutation activates this pro-oncogene and transforms normal cells to tumor cells, including lung adenocarcinoma (LUAD)." (PMID 36358651, 2022). "KRAS is located on the 12p12.1 chromosome and mutations occur in around 30% of lung adenocarcinomas." (PMID 34944952, 2021). "Concurrent mutations in STK11/KEAP1 act as a major driver in primary resistance to PD1 blockade in KRAS-mutated lung adenocarcinoma." (PMID 34204917, 2021). "KRAS G12C (glycine 12 to cysteine) mutation accounts for ~50% of all KRAS mutations, and is detected in approximately 11–16% of patients with lung adenocarcinoma." (PMID 34064352, 2021). "For example, an early study of lung adenocarcinoma patients showed that the KRAS mutation in code 12 is an unfavorable prognostic factor." (PMID 34607583, 2021). "We used the TCGA Lung Adenocarcinoma PanCancer Atlas and TCGA Provisional Lung Adenocarcinoma datasets to select the proportion of patients with KRAS mutations in codon 12 (G12C, G12D, or G12V) for further study." (PMID 33514834, 2021). "Among these, KRAS-G12D is the leading mutation in pancreatic (45%) and colorectal adenocarcinoma (45%), while KRAS-G12C mainly occurs in lung adenocarcinoma (46%)." (PMID 34607583, 2021). "Mutations in KRAS have been shown in up to 30% of lung adenocarcinomas and in approximately 5% of the squamous-cell carcinoma subtype with a higher incidence occurring in current or former smokers than in never smokers." (PMID 34684076, 2021). "Approximately 20% of lung adenocarcinomas harbor KRAS mutations, an oncogene that drives tumorigenesis and has the ability to alter the immune system and the tumor immune microenvironment." (PMID 35096591, 2021). "CT radiomics was weakly predictive for KRAS mutation status in 763 lung adenocarcinoma patients from four institutions (AUC = 0.63, temporally independent validation)." (PMID 34208595, 2021). "KRAS alterations have been found to be strictly associated with lung adenocarcinoma development and smoking." (PMID 32948832, 2021). "Mutations in KRAS are the most frequently observed molecular alterations in patients with lung adenocarcinoma, accounting for approximately 30% of cases." (PMID 33922215, 2021). "Kirsten rat sarcoma viral oncogene homolog (KRAS) mutation is frequently detected in lung adenocarcinoma and closely related with smoking status." (PMID 33435990, 2021). "Ethnicity differences are known to contribute to different rates of EGFR and KRAS mutation in lung adenocarcinoma." (PMID 34026636, 2021). "KRAS mutational data were described in a review of 513 lung adenocarcinomas from Brazilian patients profiled by NGS." (PMID 33632153, 2021). "Some studies have revealed that EGFR and KRAS mutations are mutually exclusive in lung adenocarcinoma, the mechanisms of which need to be investigated in more depth." (PMID 34447695, 2021). "Across the forty-four oncogenic KRAS mutations identified, 90% occur at codon 12, with G12C (40%) and G12V (22%) mutations being the most frequently observed in lung adenocarcinomas collectively." (PMID 34573384, 2021). "Somatic mutation of LKB1 occurs in approximately 20% of lung adenocarcinomas and 30% of KRAS-mutant lung adenocarcinomas, whereas LKB1 inactivation is present as a germline mutation of the autosomal dominant disorder, Peutz–Jeghers syndrome." (PMID 35008669, 2021).
lung adenocarcinoma (continued). "A similar observation was reported in KRAS mutation induced lung adenocarcinoma, in which disruption of STAT3 induced tumorigenesis." (PMID 34047814, 2021). "MEK is among the most common targets in the MAPK pathway, but MEK inhibitors have been largely disappointing in this context, proving to be of a very limited activity in patients with lung adenocarcinoma harbouring KRAS mutations." (PMID 34064232, 2021). "In our cohort, 10 cases with KRAS gene mutation were detected in 152 patients with stage IV lung adenocarcinoma, with a mutation rate of 6.58%, slightly lower than the reported level." (PMID 33997043, 2021). "Meanwhile, lung adenocarcinomas and colorectal adenocarcinomas are enumerated to compare with pancreatic ductal adenocarcinomas, aiming to indicate the specificity of KRAS mutations in dictating tumoral immune milieus among these cancers." (PMID 34069772, 2021). "The frequency of the distinct types of KRAS mutations in lung adenocarcinoma vary, with G12C, G12V, and G12D being the most frequently observed among different studies worldwide." (PMID 34684076, 2021). "Mutational profiling of lung adenocarcinoma patients reveals Kirsten rat sarcoma viral oncogene (KRAS), epidermal growth factor receptor (EGFR), and anaplastic lymphoma kinase (ALK) as the most prominent oncogenic drivers." (PMID 34073823, 2021). "A correlation between high vimentin expression and lung adenocarcinoma tumors bearing KRAS-G12C mutation was also observed." (PMID 34198671, 2021). "KRAS is frequently mutated in solid tumors such as pancreatic ductal adenocarcinomas (82%), colorectal carcinomas (41%), and lung adenocarcinomas (32%)." (PMID 33809714, 2021). "The KRAS mutation is common in smoking lung adenocarcinoma patients with frequency between 12 and 36%." (PMID 33549031, 2021). "Nevertheless, our findings strongly encourage the notion that different genotypes, specifically the presence of the KRAS WT allele in KRAS mutant lung adenocarcinomas, prominently affect signaling events and response to treatment." (PMID 34573384, 2021). "Our findings suggest that loss of WT KRAS impacts on signaling events and druggable targets in KRAS mutant lung adenocarcinomas." (PMID 34573384, 2021). "We successfully established nine PDX mice, from which lung adenocarcinoma tumors bearing the KRAS-G12C mutation were the most frequently grafted." (PMID 34198671, 2021). "KRAS mutations have been reported as predictors of the response of lung adenocarcinoma patients receiving platinum-based chemotherapy." (PMID 33909629, 2021). "We decided to use the Kraswt/LSL-G12D strain, because it has been widely used by others to generate genetically engineered mouse models of diseases caused by hyperactive KRAS signaling, such as lung adenocarcinoma and pancreatic ductal adenocarcinoma." (PMID 34156985, 2021). "A representative example of this bimodal distribution was shown by the top ranking comparison, i.e., lung tumors driven by mutations of either the EGFR or the KRAS oncogenes, which characterize two distinct genomic subtypes of lung adenocarcinoma." (PMID 34344431, 2021). "Because of its high frequency in lung adenocarcinoma, several preclinical and clinical investigations have been conducted seeking effective therapeutic approaches targeting KRAS mutations but, for many years, these efforts have been unsuccessful." (PMID 35004317, 2021). "For example, KRAS mutation was found in 30 % of lung adenocarcinoma patients, while BRAF mutation was less frequent." (PMID 33593390, 2021). "Suppressing the SLC7A11/glutathione axis resulted in synthetic lethality in lung adenocarcinoma with mutated KRAS." (PMID 34531924, 2021).
lung adenocarcinoma (continued). "It has been reported that CPS1 promotes pyrimidine synthesis in the aggressive subset of lung adenocarcinoma with mutant KRAS plus LKB1 loss and supports tumor growth." (PMID 33493519, 2021). "Third, ALK rearrangements are almost always mutually exclusive with other driver mutations, such as EGFR and KRAS mutations in lung adenocarcinoma." (PMID 33738250, 2021). "A systematic review and meta-analysis including 3,620 patients has shown that KRAS mutations confers a significantly worse prognosis in patients with lung adenocarcinoma." (PMID 35004317, 2021). "We also confirmed this observation in another lung adenocarcinoma cell line with inducible MET expression that we generated starting from the KRAS-mutated A549 cell line." (PMID 34298655, 2021). "It is of note that MET and HER2 amplifications are also relatively frequent in KRAS mutant lung adenocarcinomas, while EGFR or BRAF co-occurring mutations are very rare (~1%)." (PMID 32725342, 2020). "This study aimed to investigate methylated Homeobox A9 (meth-HOXA9) as an approach to detect ctDNA in advanced lung adenocarcinoma and compare it with mutated Kirsten rat sarcoma viral oncogene homolog (mut-KRAS) in order to determine the mutual agreement." (PMID 33322500, 2020). "KRAS mutation frequencies are relatively stable worldwide in various cancer types with the one exception of lung adenocarcinoma." (PMID 32725342, 2020). "In COSMIC, the KRAS G12D and G12V mutations are reported to occur in 3.3% and 4.1% of lung adenocarcinomas but were detected in 47.6% and 57.1% of lung adenocarcinomas analyzed by ACB‐PCR, respectively." (PMID 31469467, 2020). "Almost 30% of adenocarcinomas of the lung are driven by an activating Kirsten rat sarcoma viral oncogene homolog (KRAS) mutation." (PMID 32560574, 2020). "Conversely, driver KRAS mutations are mostly detected in lung adenocarcinomas in life-long smoker patients." (PMID 32158759, 2020). "High expression levels of survivin, encoded by the BIRC5 gene, in KRAS-mutant lung adenocarcinomas are significantly associated with poorer patient outcomes." (PMID 32678871, 2020). "Intriguingly, the increased PIERCE1 expression in lung adenocarcinoma was found to have significant (P < 0.05) correlations with KRAS mutation status." (PMID 32728173, 2020). "The permanent damage to DNA caused by tobacco carcinogens obtained during smoking is the main source of most KRAS mutated lung adenocarcinomas." (PMID 32342665, 2020). "KRAS mutant lung adenocarcinoma patients with concurrent inactivating mutations in the tumor suppressor genes of KEAP1 and STK11 have demonstrated lower clinical response rates treated with standard chemotherapy or immunotherapies." (PMID 32560187, 2020). "KRAS mutation is a major oncogenic driver for lung adenocarcinoma (LUAD); mutationally activated KRAS strikingly increased SLC7A11 expression in an NRF2-dependent manner." (PMID 33425217, 2020). "While the G12C mutation is prevalent in KRAS-mutant lung adenocarcinoma (~46%), this mutation is found in only 2% of PDAC13." (PMID 32576853, 2020).